TNF (tumor necrosis factor)
Diseases named in the same sentence as TNF in open-access papers (continued):
Sharing a sentence is not in itself a finding about the gene and the disease.
cancer (continued). "Variations were observed in the proportion of monofunctional CD4 T cells producing TNF, particularly higher in individuals without cancer and patients treated with chemotherapy alone, while those treated with immunotherapy or chemoimmunotherapy predominantly produced IFNγ." (PMID 39257577, 2024). "But no cancer patients responded to i.v. infusion of recombinant TNFα in phase II clinical trials." (PMID 39105847, 2024). "Furthermore, anti-TNFα therapy after cancer diagnosis did not influence recurrent or new primary cancer development." (PMID 39713142, 2024). "Although, the study also found that overexpression of Mb-TNF-α on BC cells led to a significant increase in the production of surface PD-L1 through the TNFR2/p38/NF-κB-p65/Akt pathway; this ultimately hindered the effectiveness of PD-1 expressing CAR T cells in eliminating cancer." (PMID 39609700, 2024). "Moreover, it is noteworthy to mention that exercise intensity appears to have an important role in the regulation of cancer-related inflammation, as high-intensity exercise has been shown to lead to milder increases in C-reactive protein (CRP) and TNF-α in the plasma of breast cancer patients." (PMID 38136400, 2023). "Certain systemic inflammatory markers, such as C-reactive protein (CRP), tumor necrosis factor alpha (TNF-α), interleukin-6 (IL-6), neutrophil-to-lymphocyte ratio (NLR), and platelet-to-lymphocyte ratio, are known to play a prognostic role in various types of cancer following surgery." (PMID 38137474, 2023). "Moreover, ferroptotic cancer cells release excess fatty acids into the TME, effectively inhibiting CD8+ T and NK cell efficacy and cytokines secretion, such as IFN-γ, tumor necrosis factor α (TNF-α) and peroxisome activator receptor-γ (PPAR-γ)." (PMID 38007476, 2023). "It was reported that ferroptosis cancer cells and non-cancer cells could release HMGB1, and then activate co-cultured BMDMs (bone marrow-derived macrophages) to secrete proinflammatory cytokine tumor necrosis factor alpha (TNF-α) via the HMGB1-AGER signaling pathway." (PMID 37325669, 2023). "Indeed, release of TNF-α by bone marrow derived cells in response to chemotherapy treatment has been observed, which leads to the activation of Nuclear factor kappa B (NFκB) and secretion of CXCL1/2 by cancer cells." (PMID 37182144, 2023). "The levels of TNFα, IL-1β, IL-6, and IL-12 were not affected by the cancer cell spheroids." (PMID 37445941, 2023). "We determined the cut-off values, sensitivities, and specificities of VEGF-A, TNF-α, CCL2, IL-6, and IFN-γ as biomarkers to investigate whether their plasma levels could distinguish cancer in anti-TIF1-γ antibody-positive DM patients and reflect the presence of cancer through the ROC curves." (PMID 36357631, 2023). "In the ORAL Surveillance study (NCT02092467), the incidence of cancer and major adverse cardiovascular events (MACE) were compared among groups of patients receiving tofacitinib 5 mg twice daily, tofacitinib 10 mg twice daily and a tumor necrosis factor inhibitor." (PMID 38138551, 2023). "Indeed, accumulative data suggest that the risk for recurrent and new cancer in patients with a history of cancer is not increased by thiopurines and anti-TNF agents." (PMID 36831424, 2023). "We uncovered heterogeneity in the distribution of cancer cells and molecular clues that are likely resulting from direct interactions with CAR T cells, for example, revealing immune modulatory responses such as increased antigen processing and presentation, TNF pathway activity, and HLA expression." (PMID 38067255, 2023). "M2 macrophages cultured without activation factors (w/o) after interaction with cancer cell spheroids had increased IL-1β (from (w/o) M2 90 pg/mL to S + (w/o) M2 136 pg/mL, p = 0.0009), IFNβ (from 0 to 0.6 ng/mL, p = 0.0300), and TNFα (from 98 to 131 pg/mL, p = 0.0007) cytokine secretion." (PMID 37445941, 2023).
cancer (continued). "Therefore, a better understanding of the TNF-related lncRNAs in GBM and the clinical and immunological characteristics based on its signature may help optimize cancer immunotherapy." (PMID 37153654, 2023). "In summary, based on available evidence, there is no additional increased risk of new or recurrent cancer with thiopurine, MTX, or biologic therapy, including anti-TNF and VDZ, in IBD patients with a history of previous cancer beyond the known risk in general IBD patients (without previous cancer)." (PMID 36983432, 2023). "Genome wide mRNA expression profile on M-MDSCs from three suppressive and four non-suppressive PDAC patients demonstrated an overall cancer-related gene signature including increased TNFα signaling via NF-κB, inflammatory response, IL6 JAK/STAT3 signaling and apoptosis categories." (PMID 37091970, 2023). "Therefore, anti-TIF1-γ antibodies, VEGF-A, TNF-α, CCL2, IL6, and IFN-γ could have essential roles in indicating the presence of cancer in anti-TIF1-γ antibody-positive DM patients." (PMID 36357631, 2023). "Upon cancer cell recognition, CAR T-cells act via multiple cytotoxic mechanisms, involving the release of perforins and granzymes, Fas ligand signaling, and secretion of inflammatory cytokines, such as the Tumor Necrosis Factor α (TNFα) and Interferon γ (IFNγ)." (PMID 37998753, 2023). "Therefore, we hypothesized that VEGF-A, TNF-α, CCL2, IL-6, and IFN-γ could distinguish cancer among anti-TIF1-γ antibody-positive DM patients." (PMID 36357631, 2023). "In healthy cells and cancer cells with soft defects, APM and MHC I genes can be induced by the IFN regulatory factor 1 (IRF-1), NF-κB, and the NOD-like receptor family caspase recruitment domain-containing 5 (NLRC5) in response to stimulatory cytokines such as TNF-α and IFN-γ." (PMID 38067396, 2023). "Rubiyunnanins H has been reported for its cytotoxic activity in in vitro cultures of cancer cell lines, as well as its ability to inhibit nitric oxide production in the LPS model and IFN-Υ-induced RAW 264.7 murine macrophages, and to inhibit NF-κB and TNF-α activation." (PMID 37514215, 2023). "Tumor necrosis factor receptor 2 (TNFR2), one of the two receptors that mediate the biological function of TNF, is involved in cancer cell growth, and is high expressed in exhausted CD8T cells and tumor-infiltrating regulatory T cells (Tregs) in a variety of cancers." (PMID 38161697, 2023). "In colorectal cancers, NF-κB activation in response to TNFα has been reported to induce the expression of EZH2, leading to the inhibitory promoter hyper-methylation of pro-apoptotic protein kinase cδ binding protein (PRKCDBP) and resultant increased growth of cancer cells." (PMID 36899924, 2023). "In addition, TAMs highly express TGF-β and TNF-α, promoting EMT and cancer stemness." (PMID 36831498, 2023). "Regarding data concerning new biologic therapies, a recent multicenter retrospective study included 538 IBD patients and compared the risks of incident cancer in patients with a history of non-GI cancer and receiving thiopurines (27%), anti-TNF (21%), or VDZ (9%)." (PMID 36983432, 2023). "Moreover, the xenograft tumors created from the cancer cells treated with SP showed a higher level of pro-inflammatory cytokines (IL-4β, IL-6, IL-8, IL-11, IL-12, TNF-α, and transforming growth factor β [TGF-β]) compared with those generated from cancer cells treated with PBS." (PMID 36685035, 2023).
cancer (continued). "TNF was significantly hypomethylated in 15 cancers, IL6 was significantly hypomethylated in 14 cancers, and BMP4 was significantly hypermethylated in 12 cancers, indicating that these important genes were regarded in a stably consistent manner among different types of cancer." (PMID 36945884, 2023). "Interestingly, the cytokine cocktail of IFN-γ and TNF was not able to permanently arrest the cancer cells." (PMID 35326515, 2022). "In addition, this analysis revealed the presence of several differentially expressed transcripts encoding key components of signal transduction cascades frequently found deregulated in several human cancers, including mTOR, KRAS, and TNF-α/NF-kB signaling pathways." (PMID 35918402, 2022). "The balance and interactions between the different members of the TNFα-TNFR family – as well as their cross-talk with other factors of the TME and with different therapy modes – may dictate the path that this network takes in terms of cancer progression." (PMID 35663982, 2022). "Multiple cytokines in tumor microenhractures such as TNF-α, IFN-γ, IL-6, and IL-10 play a synergistic role by increasing the expression of IDO1, affecting catabolism of tryptophan, and promoting immunosuppressive response, which in turn promotes the initiation of cancer." (PMID 35444235, 2022). "During inflammatory tissue responses, MAP4K4 also promotes increased vascular permeability and leukocyte adhesion downstream of tumor necrosis factor alpha (TNFα) signaling, indicating a broader function of MAP4K4 in vascular biology that may contribute to pathogenesis and cancer." (PMID 36568222, 2022). "Chemokines recruit CTL, natural killer (NK), NK-T cells, and macrophages, then facilitate infiltration into cancer tissue via a chemotactic gradient, eliciting directional migration in response to IFN-γ, which is synergistically augmented by tumor necrosis factor-α (TNF-α)." (PMID 35493527, 2022). "When redirected against αCD3-coated P815 cancer cells, Siglec-7+ CD8+ T cells demonstrated a higher cytotoxic capacity than their Siglec-7 negative counterparts, and co-stimulation with αCD3 and αCD28 mAbs resulted in stronger IFN-γ and TNF-α production in Siglec-7+ CD8+ T cells." (PMID 36211376, 2022). "Salivary levels of Interleukin-1α (IL-1 α), IL-6, IL-8, Vascular-Endothelial Growth Factor- α (VEGF- α) and Tumor Necrosis Factor- α (TNF- α) can support analysis of the progression of premalignant lesions of the tongue and could be used for cancer screening and early diagnosis." (PMID 36412636, 2022). "However, many inflammatory cytokines, such as IL-1, IL-6, IL-12, TNF-α, secreted by M1 macrophages are also important mediators of EMT, which could improve cancer-cell motility and invasiveness." (PMID 35794526, 2022). "In TP microglia, the principal regulator LTF is found to regulate TNF, TLR, chemokine, B-cell receptor signaling pathways and processes such as transcriptional misregulation, natural killer cell mediated cytotoxicity, phagocytosis and carbon metabolism in cancer." (PMID 34976314, 2022). "The proliferation of cancer cells could be inhibited by BMS but enhanced by TNF-α in the absence of PMCs." (PMID 35918337, 2022). "However, some cancers can be both responsive and non-responsive to Smac mimetics, irrespective of their TNF-α status." (PMID 35406442, 2022).
cancer (continued). "Furthermore, KEGG pathway enrichment analysis revealed that 7 pathways were enriched as follows: pathways in cancer, cAMP signaling pathway, metabolic pathways, PPAR signaling pathway, TNF signaling pathway, PI3K-Akt signaling pathway, and AGE-RAGE signaling pathway in diabetic complications." (PMID 36310619, 2022). "Several adjunctive therapies have been suggested to enhance the efficacy of cryosurgery, namely, chemical adjuvants such as cancer chemotherapeutic agents, AFP I, amino acid adjuvants such as glycine and tumor necrosis factor alpha (TNF-α) have all been investigated for this purpose." (PMID 38647561, 2022). "Setting the hallmarks of cancer as the reference gene sets, GSEA demonstrated that hallmarks such as epithelial-mesenchymal transition and signaling pathways like NOTCH signaling, KRAS signaling, and TNFα signaling via NF-κB were significantly enriched in the low DLL3 expression group." (PMID 36338696, 2022). "Since IL-1β, TNF-α, and IFN-γ cytokines are believed to mediate cytotoxicity of IL-2 based immunotherapies, mutant IL-2 with reduced binding to the high-affinity IL-2R may be more effective and less toxic for cancer treatment." (PMID 35354847, 2022). "However, a recent observational study confirmed lack of association between the use of anti-TNF, anti-CD20, or anti-IL6 and malignancy compared to DMARDs naïve patients." (PMID 36104053, 2022). "SPI1, as the key transcription factor for the network, may shape a positive-feedback network with the signaling from TYROBP/FCER1G or environmental TNF-α/IFN-γ, then furtherly initiate the whole SPI1-TYROBP-FCER1G network to regulate the immune infiltration and cancer prognosis." (PMID 35078433, 2022). "Therefore, antibiotics that kill microbiota to reduce the level of LPS and the related TNFα should not be used together with an IAP antagonist for cancer therapy." (PMID 36119107, 2022). "Type 1 conventional CD103+ migrating DCs are antigen-presenting cells (APCs) that elucidate CTLs before cancer cell detection via three different mechanisms: cancer antigen adhered to MHC-I, co-stimulatory molecules (CD80/86 and CD28/152), and pro-inflammatory cytokines (IL-12 and TNF-α)." (PMID 36560420, 2022). "SH-SY5Y, as with other cell cancer lines, may not enter true apoptosis (initiation of a programmed cell death cycle) in response to TNF-α, since cancer cell lines are “immortalized” (i.e., do not have a death program)." (PMID 35743863, 2022). "This could be one especially beneficial aspect for the use of MCs as an autologous source for cell-based cancer immunotherapy by ensuring the TNF-α only enters the cancer cells attached to the MCs and is not released systemically." (PMID 35740607, 2022). "However, our MTT assay exhibited that a combination of TNF-α, IFN-γ and LPS could induce cell proliferation and colony forming assay, which is an inflammation in the cancer microenvironment through the activation of NF-κB." (PMID 35681644, 2022). "This inflammatory response towards cancer cells supports the infiltration of neutrophils, which promotes cancer progression via the secretion of transforming growth factor-β (TGF-β), tumor necrosis factor (TNF)-α, metalloproteinase 9 (MMP9), reactive oxygen species (ROS), and nitric oxide (NO)." (PMID 36142615, 2022). "Therefore, the blockade of IFNs, TNF-α, IL-6, and IL17 may be a useful therapeutic approach to modulate the severity burden of cancer patients." (PMID 36550571, 2022). "As predicted, no TNF-α was detected in cancer cells co-cultured with psIgE-sensitized MCs." (PMID 35740607, 2022).
cancer (continued). "As research in this direction advanced, TNFα has been identified as a most powerful pro-cancer cytokine in many malignancies, suggesting that inhibitors of TNFα and/or its receptors (TNFR) could be applied in cancer treatment, alone or together with other modes of therapy." (PMID 35663982, 2022). "The anti-cancer activity was assessed in histological preparations of breast organs, CD4+/CD8+ T cells from spleen organs, and several essential cytokines involved in breast cancer, such as IL-1, IL-6, TNF-α, IFN-γ, TGF-β, and IL-10, in the blood serum of mice." (PMID 35765486, 2022). "Thus, we comprehensively measured representative inflammatory mediators, including IL-1β, IL-6, IL-10, IL-12p70, TNF, PGE2, and VEGF concentrations in the saliva of patients with cancer, which is convenient to measure, less invasive to collect, and can be done repeatedly." (PMID 35476641, 2022). "To evaluate whether the death of cancer cells was due to stimulation of the laNK92 cells by BiKE, we measured the concentrations of cytotoxic proteins and cytokines, including Perforin, Granzyme B, IFN-γ, and TNF-α during the ADCC experiment." (PMID 36685519, 2022). "The regulatory complexity of PRC2+-CGI genes in cancer was also evident from the types of biological pathways we identified among these genes compared to other CGI genes, including important cancer-related pathways such as EMT, KRAS signalling, and TNFα signalling and inflammatory response." (PMID 33931649, 2021). "Strikingly, GSDMB expression is increased in cancer cells stimulated with cytokines, including interferon (IFN)-γ and tumor necrosis factor (TNF)-α, which makes us speculate that cytokine production and cytotoxic mechanisms cooperate in inducing GSDMB-mediated pyroptosis in cancer cells." (PMID 33406603, 2021). "Similarly, adipocytes may promote osteoclastogenesis by secreting tumor necrosis factor α (TNF-α) and may induce proliferation with leptin, which impairs the dormant state of quiescent cancer cells." (PMID 34685686, 2021). "In Pt.3, with a shorter survival, we observed during treatment a decrease in nonclassical monocytes, which contribute to cancer immunosurveillance through NK cell recruitment and activation and are the primary producers of the inflammatory cytokines IL-1β and tumor necrosis factor-α (TNF-α)." (PMID 33430142, 2021). "Their results suggest that surgical and metabolic response to an IA justify the adoption of an entirely laparoscopic approach performing a right colectomy for cancer, but the role of other inflammatory mediators, such as IL-1β, IL-10, IL-13, TNFα and insulin, was not considered." (PMID 33958669, 2021). "However, the ILP system is cumbersome and does not address its limitation to use TNF-α systemically to improve the efficacy of cancer treatments." (PMID 33986746, 2021). "TNF-α induces an activation of corresponding TNF-α receptor (TNF-α R), various downstream signaling pathways including the c-Jun N-terminal kinase (JNK) and nuclear factor- kappa B (NF-κB) pathways and subsequent epithelial-mesenchymal transition (EMT) in many types of cancer cells." (PMID 33730072, 2021). "However, in human non-cancer colon fibroblast cells, GAE promoted anti-inflammatory activities, which was accompanied by the reduction of intracellular ROS and the inhibited expression of TNF-α, IL-1β, IL-6, and NF-κB." (PMID 33664749, 2021). "However, several are useful biomarkers of systemic dysfunction when unchecked inflammation does not resolve, including angiogenin, IL-1β, IL-6, IL-17, osteopontin, osteoprotegerin, RANTES, TNF-α and TGF-β, linking persistent inflammatory mechanisms to arthritis, type 2 diabetes, obesity and cancer." (PMID 33815289, 2021).